KLF9 (KLF transcription factor 9)
Diseases named in the same sentence as KLF9 in open-access papers (continued):
Sharing a sentence is not in itself a finding about the gene and the disease.
atherosclerosis (1 paper, 2025). A disease characterized by the build-up of fatty material and calcium deposition in the arterial wall resulting in partial or complete occlusion of the arterial lumen. "Subsequent functional annotation identified eight atherosclerosis-relevant candidate genes: transcription factors (KLF12, KLF6, KLF9, and MEF2C), epigenetic regulators (HDAC9), and signaling molecules (YAP1, SOCS6, and CDC25A)." (PMID 41373654, 2025).
cerebellar disorder (1 paper, 2012). Diseases that affect the structure or function of the cerebellum. "However, Klf9 knock-out mice show a deficit in the rotarod test, a sign of cerebellar disorder." (PMID 22586439, 2012).
chronic obstructive pulmonary disease (1 paper, 2025). A chronic and progressive lung disorder characterized by the loss of elasticity of the bronchial tree and the air sacs, destruction of the air sacs wall, thickening of the bronchial wall, and mucous accumulation in the bronchial tree. "In chronic obstructive pulmonary disease (COPD), KLF9 modulates airway inflammation by controlling pro-inflammatory cytokines and antioxidant genes, suggesting a similar function in ARDS due to the shared inflammatory mechanisms between the two conditions." (PMID 41221285, 2025).
colon adenocarcinoma (1 paper, 2023). "Our analysis of DNA methylation in tumor and normal tissues revealed that KLF9 and GATA3 were significantly higher in tumor tissues compared to normal tissues [Lung squamous cell carcinoma (LUSC), Lung adenocarcinoma (LUAD), Colon adenocarcinoma (COAD), etc.]." (PMID 37000317, 2023).
colon adenoma (1 paper, 2023). An adenoma that arises from the colon. "In another report, KLF9 mRNA and protein was significantly less abundant in human colon adenomas and adenocarcinomas than in the corresponding normal colon mucosa." (PMID 38067370, 2023).
cutaneous melanoma (1 paper, 2025). A primary melanoma arising from atypical melanocytes in the skin. "Our findings revealed that KLF9 was downregulated in cutaneous melanoma, and its higher expression was associated with improved clinical prognosis." (PMID 41301778, 2025).
dengue (1 paper, 2010). "Among the genes up-regulated in severe dengue patients are transcription factors that belong to the Kruppel-like factor family (KLF9 and KLF12), which have mainly been studied in the context of development." (PMID 20559541, 2010).
Glucose intolerance (1 paper, 2025). Glucose intolerance (GI) can be defined as dysglycemia that comprises both prediabetes and diabetes. "GTT and ITT results revealed that Klf9 deficiency improved glucose intolerance and enhanced insulin sensitivity when the mice were maintained on a high‐fat diet." (PMID 40717541, 2025).
gouty arthritis (1 paper, 2022). "LXA4 also subverted the increase in Nrf2 and Klf9 and depression of TXNRD2 in gouty arthritis rats, which is consistent with in vitro data." (PMID 36569930, 2022).
Hepatic steatosis (1 paper, 2023). Steatosis is a term used to denote lipid accumulation within hepatocytes. "Finally, adenovirus-mediated overexpression of PGC1α reversed hepatic steatosis in hepatocyte-specific Klf9 knockout mice, confirming that KLF9-mediated hepatic fatty acid oxidation is predominantly mediated through PGC-1α." (PMID 36902112, 2023). "Global and hepatocyte-specific Klf9 deletion showed normal phenotype under basal conditions but displayed hepatic steatosis and increased TG deposition in the liver when fasted for 24 h, indicating the role of KLF9 in fasting-induced hepatic fatty acid oxidation." (PMID 36902112, 2023).
immune thrombocytopenia (1 paper, 2025). "In immune thrombocytopenia (ITP) patients treated with TPO receptor agonists (TPO-RAs), KLF9 downregulation in MDSCs enhanced immunosuppressive functions by upregulating GADD34 expression." (PMID 40860800, 2025).
liver cirrhosis (1 paper, 2012). "Both KLF9 (1.7-fold, p = 0.038) and KLF10 (1.73-fold, p = 0.030) were found to be significantly higher expressed in liver cirrhosis tissue from ZZ compared to MM AAT." (PMID 22621770, 2012). "Further conformation in a different cohort of end-stage COPD lungs and in liver cirrhosis tissues showing that SNAI1, KLF9 and KLF10 are higher expressed in ZZ relative to MM AAT subjects, allows us to propose that the increased expression of zinc finger transcription factors is related to AATD." (PMID 22621770, 2012).
muscular atrophy (1 paper, 2025). The loss of muscle tissue due to inactivity or disease. "In summary, our study provides novel insights into the mechanisms underlying GC‐induced muscular atrophy and reveals that skeletal muscle induction of Klf9 expression is a mechanism underlying GC therapy‐induced muscle loss." (PMID 40717541, 2025).
myocardial ischemia (1 paper, 2023). A disorder of cardiac function caused by insufficient blood flow to the muscle tissue of the heart. "CircARAP1 aggravates myocardial ischemia-induced fibrosis and apoptosis by regulating the miR-379-5p/KLF9 axis to activate the Wnt/β-catenin pathway, and circARAP1 may be a promising therapeutic mechanism for MI/RI." (PMID 36803446, 2023).
neuroblastoma (1 paper, 2010). Neuroblastoma (NB) is the most common solid, extracranial childhood tumor. "Since the 5'-UTR study for KLF9 was also done in the mouse neuroblastoma (N2A) cell line, we used both mouse and human miRNAs in the analysis." (PMID 20205738, 2010). "Using KLF9 as an example (whose protein expression is limited to brain tissue despite the mRNA being expressed ubiquitously), we show computationally that miRNAs expressed only in HeLa cells and not in neuroblastoma (N2A) cells can bind the uAUGs responsible for translation inhibition." (PMID 20205738, 2010).
pancreatic ductal adenocarcinoma (1 paper, 2021). An infiltrating adenocarcinoma that arises from the epithelial cells of the pancreas. "Our result is encouragingly inconsistent with recent findings that point to the fact that a reduced expression of KLF9 is linked to poor survival and prognosis in pancreatic ductal adenocarcinoma and leads to tumor metastasis." (PMID 35047407, 2021).
Stroke (1 paper, 2021). Sudden impairment of blood flow to a part of the brain due to occlusion or rupture of an artery to the brain. "In addition to KLF9, we also identified STAT3 as varying significantly over space, which was also an enriched GO term in stroke cells." (PMID 33627658, 2021).
thymoma (1 paper, 2023). A neoplasm arising from the epithelial cells of the thymus. "Hypermethylation of KLF9 was associated with lower survival rates in several cancer types such as LGG, thymoma (THYM), and uterine carcinosarcoma (UCS), but hypermethylation of KLF9 in KIRC was associated with a better prognosis in KIRC." (PMID 37000317, 2023).
thyrotoxicosis (1 paper, 2022). A hypermetabolic syndrome caused by the elevation of thyroid hormone levels in the serum. "The expression of T3-regulated genes, including Hr, Dio1, Gpd2, Dbp, and Klf9, was markedly elevated in Dio3–/– fetuses compared with Dio3+/+ littermates, indicating thyrotoxicosis in all tissues." (PMID 36166296, 2022).
triple-negative breast carcinoma (1 paper, 2025). An invasive breast carcinoma which is negative for expression of estrogen receptor (ER), progesterone receptor (PR), and human epidermal growth factor receptor 2 (HER2). "The dual context-dependent roles of KLF9 in cancers like ovarian and triple-negative breast cancer highlight the need for precision approaches when targeting KLF9 or its interactors." (PMID 40860800, 2025).
type 2 diabetes (1 paper, 2023). "Genetic variants in or near the CDKAL1, KLF9, GP2, ALDH2, and ITIH4 genes are associated with obesity and genetic variants in or near the GDAP1, PTF1A, SIX3, ALDH2, and PAX4 genes are specifically associated with type 2 diabetes in East Asians." (PMID 37749090, 2023).
ulcerative colitis (1 paper, 2023). An inflammatory bowel disease involving the mucosal surface of the large intestine and rectum. "KLF9 had been identified as a diagnostic marker associated with ulcerative colitis." (PMID 38192721, 2023).
tumor (61 papers, 2007 to 2025). "KLF9 has emerged as a multifunctional regulator of endothelial cell (EC) biology, influencing pathological angiogenesis, metabolic dysregulation, and tumor-associated vascular remodeling." (PMID 40860800, 2025). "KLF9 deficiency in CAFs is often associated with increased tumor aggressiveness and poor patient prognosis." (PMID 40860800, 2025). "Similar questions are clear for tumor-associated pre-adipocytes and adipocytes and their corresponding KLF9 and KLF13 expression and actions." (PMID 38067370, 2023). "KLF9 is a suppressor of liver inflammation that underlies its tumor-suppressive effects in the liver and other tissues." (PMID 36761967, 2023). "RT-qPCR analysis showed that miR-889-5p was significantly upregulated in tumor tissues, while miR-889-5p expression was negatively associated with KLF9 expression in HCC tissues and positively associated with FABP5 expression in HCC tissues." (PMID 35816613, 2022). "Contrary to what we found in the present study, KLF9 was low expressed in CRC tumor tissues and was associated with poor prognosis." (PMID 31024853, 2019). "Mechanistically, KLF9 may influence tumor immunogenicity by modulating necroptosis-associated signals or indirectly altering chemokine secretion patterns to reshape immune cell recruitment dynamics." (PMID 40860800, 2025). "Moreover, KLF9 promotes hematopoiesis and T lymphopoiesis in zebrafish, negatively regulates B cell proliferation, and is positively associated with tumor immune cell infiltration." (PMID 38067370, 2023). "In addition, a recent study found that over-expression of KLF9 caused suppression of metastasis of HCC tumor cells, whereas knock-down of KLF9 caused the opposite effects, ascribed, in part, to KLF9 repression of the EMT pathway." (PMID 38067370, 2023). "Furthermore, the expression of KLF9 was negatively associated with tumor stage, nodal metastasis, and overall survival and disease-free survival." (PMID 35024436, 2022). "Results demonstrate that KLF9 is a suppressor of liver oxidative stress and inflammation which may underlie its tumor suppressive actions in liver and other tissues." (PMID 35406507, 2022). "Thus, we suggest that circPTPRA exerts a tumor suppressor function in BC cells by preventing the miR-636/KLF9 association." (PMID 31821171, 2019). "Our results provide support to the emerging concept of KLF9 as an important regulator of local and systemic oxidative stress and ROS-induced cell responses including inflammation, and which may underlie its tumor-suppressive effects in liver and other tissues." (PMID 35406507, 2022). "KLF9 influences the expression of uterine epithelial genes through mechanisms likely involving its transcriptional activator and repressor functions and which may underlie altered tumor biology with aberrant KLF9 expression." (PMID 18783612, 2008). "While KLF9 acts as a tumor suppressor in metastatic niches by suppressing cancer stemness and Notch1/Slug-driven aggressiveness, its paradoxical upregulation in primary tumors suggests a microenvironment-specific duality." (PMID 40860800, 2025). "Studies have indicated that KLF9 expression is often downregulated in various cancers, correlating with a more aggressive tumor phenotype and increased metastatic potential." (PMID 40860800, 2025). "Conversely, in cancer, KLF9 has emerged as a tumor-suppressor by inhibiting NF-κB, repressing metastasis-associated genes like MMP9 through chromatin remodeling and direct interference with NF-κB transcriptional activity." (PMID 40860800, 2025). "In advanced OC ascites-derived tumor spheroids, KLF9 was downregulated and inversely correlated with cancer stemness, metastasis, and poor prognosis." (PMID 40860800, 2025). "Conversely, in EC, KLF9 acts as a tumor suppressor by directly inhibiting oncogenic Wnt/β-catenin signaling." (PMID 40860800, 2025). "Regarding the tumor microenvironment, KLF9 remodels the immune landscape and suppresses CAF activation." (PMID 40860800, 2025).
tumor (continued). "Studies have shown that KLF9 can act as a transcriptional repressor in CAFs, affecting the expression of genes involved in inflammation, extracellular matrix remodeling, and tumor cell interaction." (PMID 40860800, 2025). "Several antioxidant genes, including TXNRD2, are inhibited by KLF9, thereby increasing reactive ROS levels, which negatively impact tumor development." (PMID 41301778, 2025). "Recent research has revealed the dual nature in tumorigenesis, where KLF9 can function as either a tumor suppressor or an oncogene, depending on the cellular context." (PMID 40860800, 2025). "FABP5 enhances tumour cell proliferation and migration via pathways including PI3K/AKT/mTOR and cAMP response element-binding protein (CREB)-mediated miR-889-5p signalling, which targets and suppresses the tumour suppressor Kruppel-like factor 9 (KLF9)." (PMID 41149452, 2025). "This KLF9-mediated reprogramming of macrophage behavior fosters an immunosuppressive niche that accelerates tumor metastasis, contrasting sharply with KLF9’s tumor-suppressive functions observed in other malignancies." (PMID 40860800, 2025). "In HCC, KLF9 acts as a tumor suppressor whose downregulation activates PI3K/Akt signaling, driving aggressive proliferation and invasion." (PMID 40860800, 2025). "The adipocyte paracrine secretion of ER+tumors provides estrogen precursors to support the KLF9-GR anti-tumor axis, while the high inflammatory cytokine environment of TNBC activates NF - κ B to form antagonistic interactions with KLF9." (PMID 40860800, 2025). "Collectively, KLF9 has emerged as a multifaceted tumor suppressor in HCC, counteracting oxidative stress, inflammation, EMT-driven metastasis, and epigenetic dysregulation." (PMID 40860800, 2025). "Overall, KLF9 has emerged as a critical tumor suppressor in NSCLC, with its dysregulation contributing significantly to tumor progression and immune evasion." (PMID 40860800, 2025). "Future research should clarify KLF9’s spatiotemporal Wnt control and develop tissue-specific modulators that balance physiological Wnt activity with anti-tumor effects, avoiding pathological signaling." (PMID 40860800, 2025). "In conclusion, the abnormal expression of KLF9 in different tumor types directly affects the occurrence, metastasis and survival of patients." (PMID 40860800, 2025). "In OC patients, KLF9 expression was significantly reduced in blood samples compared to controls, suggesting its potential role as a tumor suppressor." (PMID 40860800, 2025). "Study have shown that the overexpression of KLF9 significantly enhances the ability of apoptosis, and inhibits the proliferation and migration of tumor cells by regulating the transcription of metallothionein 1m (mt1m) in cholangiocarcinoma cells." (PMID 40860800, 2025). "In vivo, KLF9 silencing promotes tumor growth via GADD34-mediated recruitment of myeloid-derived suppressor cells (MDSCs), linking KLF9 loss to immunosuppression." (PMID 40860800, 2025). "Current research indicates that KLF9 exerts tumor-suppressive functions through mechanisms operating at multiple levels." (PMID 40860800, 2025). "As a transcription factor, klf9 can also activate tumor cell apoptosis through epigenetic synergistic effects." (PMID 40860800, 2025). "The exploration of KLF9 in cancer research has unveiled its significant biological implications and established its crucial role in the complex landscape of tumor biology." (PMID 40860800, 2025). "KLF9 was also found to correlate with immune cell infiltration and interact with immune-related genes, suggesting its role in modulating the tumor microenvironment." (PMID 40860800, 2025). "This reduced expression is associated with enhanced migratory and invasive capabilities of CRC cells, suggesting that KLF9 acts as a barrier against tumor progression." (PMID 40860800, 2025).
tumor (continued). "The dynamic interplay between ncRNAs and KLF9 exemplifies a sophisticated regulatory axis that fine-tunes oncogenic and tumor-suppressive programs across cancers." (PMID 40860800, 2025). "Conversely, tumor suppressors such as miR-378h, miR-125b-5p, and KLF9 were shown to inhibit KIAA1522 expression, highlighting its potential as a central therapeutic target across diverse malignancies." (PMID 41306285, 2025). "KLF9 has been found to be downregulated in various human cancers, and its overexpression can inhibit several tumorigenic phenotypes in tumor cells, such as proliferation, invasion, and anti-apoptosis." (PMID 41301778, 2025). "The interaction of KLF9 with the TME is complex and multifaceted, influencing tumor immunity, cancer-associated fibroblasts (CAFs), and angiogenesis." (PMID 40860800, 2025). "Clinical samples showed that the mRNA and protein levels of KLF9 in tumor tissues were higher than those in normal tissues, while KLF9 knockdown significantly inhibited cell proliferation and the growth of transplanted tumors in nude mice." (PMID 40860800, 2025). "Specifically, we identified KLF9, a known tumor suppressor, as a potential downstream effector of WTAP." (PMID 41301778, 2025). "Analysis of 68 paired tumor/normal samples revealed significantly lower KLF9 levels in cancerous tissues." (PMID 40860800, 2025). "KLF9 acts as a transcriptional regulator participating in tumor metabolic control through multiple mechanisms." (PMID 40860800, 2025). "KLF9 mediates tumor-suppressive effects by concurrently restraining intrinsic tumor malignancy and inhibiting the remodeling of immunosuppressive microenvironment components." (PMID 40860800, 2025). "Another study revealed that the calcium-dependent enzyme PAD4 was upregulated in CRC through direct transcriptional activation by KLF9, promoting tumor growth and metastasis." (PMID 40860800, 2025). "The lncRNA DANCR has been identified as a negative regulator of KLF9, suggesting a complex regulatory network where KLF9 functions as a tumor suppressor." (PMID 40860800, 2025). "Clinically, validating KLF9 as a prognostic biomarker or therapeutic target requires robust multi-omics integration, particularly to decipher its crosstalk with tumor microenvironments and metabolic pathways." (PMID 40860800, 2025). "In contrast, the expression of KLF9 was found to be significantly downregulated in COAD tumors as compared to the adjacent non-tumor tissues." (PMID 38164176, 2024). "Our findings demonstrate that ACTA2-AS1 functions as a tumor suppressor in PTC progression at least partly by regulating the miR-4428-dependent expression of KLF9." (PMID 38195623, 2024). "CDKN2A, GEMIN2, DLAT, and ZCRB1 were expressed at higher levels in tumors than in normal tissues, while the expression of KLF9 in tumor tissue was lower." (PMID 36909185, 2023). "That same proportion of low KLF9-expressed tumor tissues was further characterized as poorly differentiated and highly invasive." (PMID 37239940, 2023). "In A431 tumor cells, KLF9 is a repressor of the PFKFB3 (6-Phosphofructo-2-kinase/fructose-2,6-biphophatase 3) gene, which encodes a protein that stimulates proliferation and metastatic behavior in vitro." (PMID 38067370, 2023). "We measured the transcriptional level of KLF9 by real‐time RT‐PCR in 43 pairs of human HCC tumour samples and matched normal tissues." (PMID 37400979, 2023). "Conversely, KLF9 inhibits tumor stem cells, suppressing the proliferation and metastasis of tumor tissue." (PMID 36761967, 2023). "Such a tumor inductive scenario (if confirmed) can be approached in two ways, i.e., targeting the suppressors of KLF9 and KLF13 and targeting KLF16." (PMID 38067370, 2023). "Consistent with this, tumor cell levels of KLF9 and KLF13 are positive factors for overall survival of patients with clear cell renal cancer." (PMID 38067370, 2023).